OR6L2P (olfactory receptor family 6 subfamily L member 2 pseudogene)
Gene: Unprocessed pseudogene on chromosome 10 (133,430,394 to 133,431,318, reverse strand). Ensembl gene ENSG00000273327.
Diseases named in the same sentence as OR6L2P in open-access papers:
OR6L2P is named in the same sentence as 1 disease in open-access papers, as found by Europe PMC text mining. Sharing a sentence is not in itself a finding about the gene and the disease.
OR6L2P shares sentences with these, for which no sentence is quoted: autism (1 paper).